MYO1B (myosin IB)
Diseases named in the same sentence as MYO1B in open-access papers (continued):
Sharing a sentence is not in itself a finding about the gene and the disease.
metastatic tumors (1 paper, 2020). "In PCa, Myo1b, Myo6, Myo9b, Myo10, and Myo18a were expressed at higher levels in high metastatic potential cells, and especially Myo1b and Myo10 were expressed at higher levels in metastatic tumors." (PMID 33292248, 2020).
Parkinson disease (1 paper, 2023). A progressive degenerative disorder of the central nervous system characterized by loss of dopamine producing neurons in the substantia nigra and the presence of Lewy bodies in the substantia nigra and locus coeruleus. "Coincidentally, earlier studies show that LRRK2 is a key influencing factor for Parkinson disease (PD), which is significant to be associated with aging, indicating that Myo1b might be involved in the pathogenies of PD through mediating the neural cell senescence." (PMID 36654782, 2023).
prostate tumour (1 paper, 2019). "Similarly, MYO1B exon 23 (skipped in response to ESRP2) is both overall more skipped in prostate tumour versus normal, and more skipped in higher Gleason grade cancers." (PMID 31478829, 2019).
psoriasis (1 paper, 2022). An autoimmune condition characterized by red, well-delineated plaques with silvery scales that are usually on the extensor surfaces and scalp. "In this regard, it is interesting to note that AP-1 upregulates the gene expression of SQLE, STRN, EIF4E, and MYO1B might to promote the abnormality of keratinocytes and immune system to mediate the occurrence of psoriasis." (PMID 35277199, 2022).
cancer (23 papers, 2016 to 2025). A tumor composed of atypical neoplastic, often pleomorphic cells that invade other tissues. "Key genes (ACTIN1, LIMK1, CORO1C, INF2, SH3D21, CFL1, FSCN1, MYO1B) implicated in actin cytoskeleton organization were identified, suggesting their role in oral potentially malignant disorders and cancer progression." (PMID 40818124, 2025). "Additionally, MYO1B has been implicated in the progression of various malignant tumors." (PMID 41278212, 2025). "Based on the expression levels of MYO1B, we divided the cancer cases into high-expression and low-expression groups and investigated the survival rate of patients with the HNSC dataset." (PMID 39768999, 2024). "Among various human cancers, NB is among the highest MYO1B expressors, and MYO1B expression is sharply increased in multiple cohorts of NB tumors compared with normal adrenal glands." (PMID 37611092, 2023). "TPRG1-AS1 was upregulated in more than 1/3 of cancers, MYO1B in more than 2/3 of cancers, and hsa-miR-338-3p was downregulated in more than 1/3 of tumors." (PMID 37481637, 2023). "Myo1b and Myo1c are the best characterized class I myosins involved in cell migration and emergent evidence highlight their role in different types of cancer." (PMID 34974807, 2022). "Consistent with previous reports about the elevated expression in other cancers, MYO1B, MYO5A, and MYO10 levels were increased in HNSCC tissues compared with adjacent normal tissues whereas MYO5C expression was found to be downregulated." (PMID 35478939, 2022). "For instance, cancer development-related PI3K-Akt signaling, focal adhesion signaling, integrin-ECM pathways, and EMT processes were all enriched in MYO1B/MYO5A/MYO10 associated DEGs." (PMID 35478939, 2022). "For example, dysregulation of SMS may alter lipid metabolism, leading to changes in membrane composition that affect the localization and activity of MYO1B, thereby enhancing cancer cell motility and invasion." (PMID 38562924, 2024). "Myosin-1b (MYO1B) promotes cancer by targeting HIF1a and SNAI2/cyclinD160,61." (PMID 38291075, 2024). "Analysis of gene expression across multiple cancer types and their associations with cancer stage and patient survival in the TCGA-HNSC dataset identified a PYCR1 and MYO1B gene that could be a potential tumor-associated marker." (PMID 39768999, 2024). "Thus, MYO1B may play a crucial role in the pathobiology and malignant progression across diverse cancers, which remains unexplored." (PMID 37611092, 2023). "Among of them, SLC12A5, MYO1B, FBN1, ITGAV, KLF4 and USP28 were more reported to effect cell proliferation and migration in human cancers." (PMID 39951205, 2025). "Our analysis highlighted the dysregulation of both MYO1B and PYCR1 in different cancer types, especially in the HNSC dataset." (PMID 39768999, 2024). "Together, these findings strongly point to MYO1B as a transcriptional target of GREB1 in NB and other cancers." (PMID 37611092, 2023). "Here, our study uncovers that MIF secretion is controlled by MYO1B, which provides a mechanism of action as to how MIF is deployed by cancer cells for aggressive progression." (PMID 37611092, 2023). "Notably, the genes MYO1B and PYCR1 were significantly upregulated in various cancer types, especially the HNSC dataset, when compared to normal tissues." (PMID 39768999, 2024). "However, a function for MYO1B in secretome reprogramming has not been previously reported in cancer cells." (PMID 37611092, 2023). "However, the underlying molecular mechanisms mediating MYO1B functions in cancer remain poorly understood, nor is it known whether MYO1B plays a role in NB." (PMID 37611092, 2023).
tumor (21 papers, 2015 to 2025). "Although angiogenesis is essential for tumor growth and metastasis, whether the effect of Myo1b on the invasion/motility of CRC cells is associated with its proangiogenic roles is an interesting topic that needs to be further investigated." (PMID 36347835, 2022). "MYO1B enhanced tumor spread through the EMT approach, according to epithelial mesenchymal transition (EMT) characterisation." (PMID 37481637, 2023). "In support of this function, we observed a marked presence of MYO1B in membrane/vesicle structures budding off the plasma membrane of tumor cells, not only in NB cells but also in murine fibroblasts transformed by KRasG12V or EN oncogenes." (PMID 37611092, 2023). "Nevertheless, we suspect that, in addition to MIF, various other secreted proteins in MYO1B-controled secretome likely work in concert to promote NB tumor progression." (PMID 37611092, 2023). "It is up-regulated in metastatic tumor cells, and MYO1B knockdown (KD) alters cell morphology and decreases tumor cell invasion." (PMID 37611092, 2023). "Together, these data strongly support the notion that MYO1B promotes features of tumor cell invasiveness and metastatic capacity in NB cells." (PMID 37611092, 2023). "The survival time of orthotopic xenograft tumor mice was analyzed with a Kaplan–Meier curve and the results revealed that Myo1b knockdown significantly prolonged survival time of tumor-bearing nude mice." (PMID 36347835, 2022). "Herein, we investigated the expression levels of Myo1b in CRC tissues compared with matched non-tumor tissues and demonstrated the pivotal function of Myo1b in CRC progression and angiogenesis." (PMID 36347835, 2022). "In this study, we explored the potential function of Myo1b in CRC and confirmed that Myo1b facilitated CRC progression and angiogenesis by inhibiting autophagic degradation of HIF-1α, suggesting that Myo1b acts as a tumor promoter in CRC." (PMID 36347835, 2022). "In accordance with the results in vitro, silencing Myo1b dramatically inhibited tumor growth compared with NC group." (PMID 36347835, 2022). "Upregulation of HSPG2 and MYO1B in vasculature in the tumor core were validated by immunostaining in human specimens." (PMID 34228647, 2021). "In KEGG analysis results, we noticed that MYO1B, MYO5A, and MYO10 associated DEGs were enriched in PI3K-Akt signaling, focal adhesion process, and ECM-receptor interaction which were all related to tumor metastasis." (PMID 35478939, 2022). "More importantly, we demonstrated for the first time that Myo1b promoted tumor angiogenesis." (PMID 36347835, 2022). "Furthermore, miR-363 and miR-145-3p were found to be a tumor-suppressor in HNSCC or ESCC via targeting Myo1b." (PMID 36347835, 2022). "Conversely, silencing of Myo1b suppressed tumor progression both in vitro and in vivo." (PMID 36347835, 2022). "It is suggested that MYO1B may accelerate tumor growth by triggering EMT." (PMID 37481637, 2023). "Taken together, we demonstrate that circZFR promotes MYO1B exon 23 inclusion to regulate OXPHOS and enhance tumor progression through AKT-mTORC1 signaling." (PMID 37461053, 2023). "Mechanistically, Myo1b blocked the autophagic degradation of HIF-1α and then led to the accumulation of HIF-1α, thus enhancing VEGF secretion and then promoting tumor angiogenesis in CRC." (PMID 36347835, 2022). "In addition, the GSCALite database was explored based on the tumor treatment response portal (CTRP) and GDSC to assess the correlation of drug sensitivity with CCND1 and MYO1B." (PMID 37481637, 2023). "For discrimination of the normal and tumour sampling zones, we were able to derive an effective gene-based classifying model for molecular abnormality based on a panel of eight genes (MMP1, MMP12, MYO1B, TNFRSF12A, WDR66, LAMC2, SLC16A1 and PLAU)." (PMID 35327656, 2022).
tumor (continued). "In conclusion, this manuscript provided comprehensive analyses about the expression and function of MYOs in HNSCC, suggested MYO1B, MYO5A, and MYO10 as potential prognostic biomarkers in HNSCC, and revealed the potential novel roles of MYO1B, MYO5A, and MYO10 in tumor immune microenvironment." (PMID 35478939, 2022). "Among the proteomic markers, elevated levels of serum ceruloplasmin, MYO1B, salivary CPLANE1, serum albumin, HSP 27, gamma actin, SCC 1, and A4, serum SNCG and SCCAg and immune cell markers such as, IL‐6, TNF‐α, and CD4 + T cell were suitable proteomic tumor markers in detecting OSCC." (PMID 40256126, 2025). "Similar with the in vitro results, the analysis by xenograft tumor model suggested that CYT notably reduced the tumor size and growth curve of MDA-MB-231-DR cells, along with decreased level of KI-67, whereas overexpression of SRSF1 and MYO1B reversed these effects." (PMID 40176901, 2025). "Functional studies indicated that Myo1b acts as a pivotal autophagy regulator by modulating the autophagosome-lysosome fusion, which could inhibit the autophagic degradation of HIF-1α, thus enhancing VEGF secretion and then promoting tumor angiogenesis in CRC." (PMID 36347835, 2022). "Furthermore, the protein levels of MYO1B, MYO5A, MYO5C, and MYO10 in HNSCC tumor tissues and normal tissues were examined by Human Protein Atlas (HPA) database; consistently, the protein levels of MYO1B and MYO10 were dramatically enhanced in tumor tissues compared with normal tissues." (PMID 35478939, 2022).
infection (19 papers, 2009 to 2024). The state of being infected such as from the introduction of a foreign agent such as serum, vaccine, antigenic substance or organism. "Genes involved in fatty acid transport, albumin (ALB), myosin (MYO1B), and the thrombospondin receptor (CD36), were up-regulated during infection." (PMID 19216742, 2009).
endocrine system disorder (1 paper, 2017). A disease involving the endocrine system. "In the TC vs. WZS group, the highest ranking network, scoring 70, was associated with cellular movement, developmental disorder, and endocrine system disorders; this network comprised myosin VA (MYO5A), miR-145, miR-143, and myosin IB (MYO1B)." (PMID 28045116, 2017).
head and neck tumors (1 paper, 2023). "Further analysis of the database showed that MYOB was regulated by methylation in head and neck tumors, and functional enrichment analysis showed that MYO1B was involved in "actin filament organization" and "cadherin binding "." (PMID 37481637, 2023).
MYO1B also shares sentences with these, for which no sentence is quoted: cyst (6 papers); colon cancer (3); Anxiety (1); cardiovascular diseases (1); diffuse large B-cell lymphoma (1); esophageal cancer (1); inflammation (1); liver cancer (1); lung adenocarcinoma (1); lymph node metastasis (1); medulloblastoma (1); neuroblastoma (1); non-small cell lung carcinoma (1); prostate adenocarcinoma (1); thymoma (1); toxoplasmosis (1).